RN7SL183P (RNA, 7SL, cytoplasmic 183, pseudogene)
Gene: Miscellaneous RNA gene on chromosome 6 (87,845,650 to 87,845,947, forward strand). Ensembl gene ENSG00000240997.
Homologues: Orthologues: chimpanzee Metazoa_SRP (98% identical), macaque Metazoa_SRP (92% identical). Paralogues in human: RN7SL1 (84% identical), RN7SL2 (83% identical), RN7SL3 (83% identical), RN7SL357P (82% identical), RN7SL575P (80% identical), RN7SL230P (80% identical), RN7SL126P (80% identical), RN7SL14P (80% identical), RN7SL296P (80% identical), RN7SL680P (80% identical), RN7SL326P (79% identical), RN7SL408P (79% identical), and 703 more.